IL1B (interleukin 1 beta)
Diseases named in the same sentence as IL1B in open-access papers (continued):
Sharing a sentence is not in itself a finding about the gene and the disease.
Stroke (continued). "The application value of the compound on stroke was assessed, and the results of ELISA assay suggested that the compound could obviously reduce the releasing of the TNF-α and IL-1β into the plasma in a dose-dependent manner." (PMID 35711621, 2022). "Macrophages/microglia are major source of inflammatory mediators (e.g., TGF-β, IL-6, IL-1β, or TNF-α) in stroke to activate the astrocyte TLR/NF-κB inflammatory pathway and further amplify neuroinflammation to exacerbate neuronal damage and stroke symptoms." (PMID 36159395, 2022). "Also, IL-1β, IFN-γ, and TNF-α showed greater percentage decrease when stroke monocytes were involved in both trans-well and contact co-cultures, as compared to when healthy control monocytes were involved." (PMID 36277912, 2022). "The pro-inflammatory (TNF-α, IL-1β, IL-6, IL-12 p40, and MIP-1α), and the anti-inflammatory (IL-4 and IL-10) mediators were examined by ELISA in IRF5 or IRF4 CKO aged mice plasma, 3 days after stroke." (PMID 35963621, 2022). "Most researchers reported increased levels of IL-1β within 24 h after stroke onset, while others did not." (PMID 35008440, 2021). "Among the inflammatory mediators, interleukin (IL)-1β, tumor necrosis factor α (TNFα) and monocyte chemoattractant protein-1 (MCP-1) are classic factors that have been found in both experimental models and human stroke." (PMID 34327147, 2021). "This was corroborated by literature publishing that TNF-α, IL-1B, IL-6 and IL-18 also independently predicted the occurrence of PSD in the acute to subacute period, and elevated IL-6, IL-10 and TNF-α correlates with PSD at one to three months post stroke." (PMID 33919670, 2021). "The core targets of DZSM for stroke are TNF, AKT1, VEGFA, and IL-1β, which are highly correlated." (PMID 34754318, 2021). "Since NS19504 treatment promoted the outcome of stroke, we detected whether inflammation affects the significant difference between groups, and the mRNA levels of inflammation factors TNF-α, IL-1β, IL-6, IL-10, and TGF-β were examined." (PMID 34276309, 2021). "Third, IFN-γ is a potent inducer of other pro-inflammatory cytokines, such as IL-6, IL-1β and TNF-α, which may further the inflammatory response following the original stroke insult." (PMID 33919670, 2021). "In the peripheral compartment, PD did not significantly modulate myeloid trafficking compared to the levels observed in the stroke-only group, nor were plasma concentrations of IL-1β, IL-17A, and GM-CSF altered." (PMID 30794103, 2020). "In the Western blot assessment, the protein levels of TNF-α and IL-1β were increased, whereas no change was detected in IL-6 and IL-10 protein levels in the stroke mice at 3 days after stroke." (PMID 32010477, 2020). "In the context of recovery after stroke, these effects of IL-1β on BDNF may be a significant block to recovery as BDNF plays a critical role in neural plasticity and recovery after stroke." (PMID 33275615, 2020). "In this study, an array of inflammatory cytokines including IL-1β, TNF-α, IL-6, cyclooxygenase (COX)-2, monocyte chemoattractant protein (MCP)-1, and chemokine (C-X-C motif) ligand 1 (CXCL1) at 6, 24, 48, and 72 h after stroke were analyzed by qRT-PCR." (PMID 32867781, 2020). "The results showed that MCAo increased the levels of pro-inflammatory cytokines while RIPC significantly decreased the levels of pro-inflammatory IL-1β, IL-6 and IFN-γ in the peripheral blood and that of IL-1β and IFN-γ in penumbra tissue 48 h post-stroke in aged rats." (PMID 32210788, 2020). "Proteomics analysis of isolated EVs revealed a more proinflammatory phenotype in the “stroke EVs”, while coincubation with THP-1 monocyte-derived macrophages induced elevated mRNA expression of proinflammatory cytokines TNFα, IL-1β and chemokines CXCL-1 and CCL-2." (PMID 33019535, 2020). "Stroke mice receiving the hypothermic treatment showed a lower neurological severity score and a decreased expression of inflammatory factors including TNF-α, MMP-9, and IL-1β." (PMID 33381263, 2020).
Stroke (continued). "IL-1β and TNF-α are known to play a proinflammatory role after stroke and worsen stroke outcomes." (PMID 32802081, 2020). "Treatment however, with DS2 did not have any effect on IL-1β levels with levels remaining similar to stroke + vehicle controls." (PMID 31736685, 2019). "Compared to stroke animals, rats receiving hypothermia therapy had a lower p-CDK5 level, indicating that hypothermia suppressed the activation of the CDK5 signaling pathway, consequently decreasing IL-1β generation." (PMID 31644666, 2019). "MCC950 ameliorated deficits in hippocampal-dependent memory after diabetic-stroke in rats, through inhibition of the NLRP3 inflammasome with decreased IL-1β expression, lower blood-brain barrier permeability, and reduced cell death of the neurons in the CA1 and DG regions of the hippocampus." (PMID 31174550, 2019). "Ischemic damage and MSC transplantation after stroke did not induce the Iba-1+ cells to produce TNF-α or IL-1β either." (PMID 30405724, 2018). "With regard to therapeutic intervention, G-CSF, IL-1β, IP-10, MCP-1, MIP-1α, MIP-1β, RANTES, TNF-α, MMP-2, and MMP-8 were substantially reduced in OPN-/- mice seven weeks following stroke, and these mice exhibited less secondary neurodegeneration in the peri-infarct location." (PMID 30417081, 2018). "Protein levels of caspase-1, ASC and IL-18 were higher in the serum of stroke patients when compared to the control samples, whereas levels of IL-1β were not significantly different." (PMID 30233311, 2018). "Furthermore, activated astrocytes can produce an array of pro-inflammatory cytokines, including IL-1β and TNF-α, which promote inflammation after stroke." (PMID 29976213, 2018). "Stroke-induced monocyte dysfunction resulted in an increase of the interleukin-10 (IL-10) level as well as a decrease of the interleukin-6 (IL-6), tumor necrosis factor-α (TNF-α) and interleukin-1β (IL-1β) levels." (PMID 29636059, 2018). "To confirm the inflammatory environment initiated by our stroke model, we measured increased proinflammatory cytokines IL-1β, IL-6, and Tnfα in the ipsilateral cortex, and this did not significantly change with 10 mg/kg decernotinib." (PMID 28790974, 2017). "However, after sex stratification we found that IL1A, IL1B, IL6, IL8, TNF and other 13 anti-stroke targets were all up-regulated in male patients." (PMID 27672514, 2016). "IL-1β and TNF-α dramatically affect infarct evolution in experimental stroke models." (PMID 27544687, 2016). "National Institute of Health Stroke Scale (NIHSS); hemorheological detection; coagulation function; and serum inflammatory markers, tumor necrosis factor-alpha (TNF-α), interleukin-1β (IL-1β), and interleukin-6 (IL-6), were used to investigate the effects before and 14 days after the treatment." (PMID 26074992, 2015). "Further, serum IL-1β, IL-1ra, and IL-9 levels measured within 72 h after stroke predicted fatigue symptoms, but not depressive symptoms." (PMID 23675319, 2013). "Inflammatory cytokines, such as IL-1β, IL-6, and TNF-α, are secreted by activated microglial cells and macrophages in stroke lesions and induce the expression of chemokines, which recruit more circulating monocytes/macrophages into lesions and lead to further brain damage." (PMID 23431245, 2013). "Interestingly, large stroke and ICH resulted in a prolonged increase of IL-6 and IL-1β concentration until follow-up, resulting in a still 2-fold increase of IL-1β compared to controls." (PMID 24069356, 2013). "Chronic increases in IL-1β expression in the brain led to leukocyte infiltration and increased MCP-1 and ICAM-1 expressions in a mouse model, which is a phenotype also seen in stroke lesions." (PMID 23431245, 2013). "The administration of anti-IL-1β antibody (600 μg/day) slightly, but not significantly, delayed the onset of stroke compared with control (P = 0.232 by the Log-Rank test)." (PMID 23326018, 2012).
Stroke (continued). "Chronic increase in IL-1β expression in the brain led to leukocyte infiltration and increased MCP-1 and ICAM-1 expressions in a mouse model, which is a phenotype also seen in stroke lesions." (PMID 23326018, 2012). "The induction of IL-1α, IL-1β, TNFα MCP-1, RANTES, G-CSF, KC mRNA and increased MCP-1, RANTES, G-CSF protein levels in the brain after systemic LPS challenge are likely to result in a primed proinflammatory response by the time experimental stroke is induced." (PMID 22114895, 2011). "Pro-inflammatory cytokines such as IL-1β and TNF-α have been proposed as potent mediators of neuronal death in several neurodegenerative diseases like AD, traumatic brain injury, epilepsy, Parkinson's disease, stroke, HIV and JE." (PMID 21034511, 2010). "However, it is interesting to note that non-specific antagonism of P2X receptors by PPADS, and the inhibition of IL-1β, and COX-2, have all been reported to be effective in animal models of stroke and other neurodegenerative disorders." (PMID 17367517, 2007). "The evidence indicates distinct prognostic patterns: biomarkers of inflammation (e.g., TNF-α, IL-6, IL-1β) and neuronal or glial damage (e.g., S100B, GFAP, NSE, NfL) tend to correlate with less favorable outcomes, especially when measured in the acute phase of a stroke." (PMID 41598337, 2026). "Among them, MG6 cells expressed high levels of Cxcr2, S100a8, interleukin (IL)‐1β, and matrix metallopeptidase 9 (MMP9), demonstrating a unique “neutrophil‐like” phenotype and were considered to represent a stroke‐specific state of microglia in the aged brain after stroke." (PMID 40843131, 2025). "Additional processes—such as IL-1β-induced glycolytic shifts, BBB effects that facilitate lipid/cytokine trafficking, and matrix metalloproteinase upregulation—may further couple cytokine and lipid pathways in stroke." (PMID 41301455, 2025). "An important phenomenon after stroke is the systemic immunosuppressive effect, which usually manifests as splenic atrophy accompanied by increased apoptosis or cellular dysfunction, along with the suppression of numerous inflammatory factors, including IL10, IL-1b, TNF-α, and IL-6." (PMID 38637850, 2024). "Studies regarding the effects of IL-1β on stroke patients are not conclusive; they indicate both its inflammatory effect, contributing to the increase in the area of damage during a stroke, and its positive effects in terms of neuroprotection and neuroplasticity." (PMID 38790409, 2024). "Therefore, the detection and targeted intervention of concentrations of IL-1β, IL-6 and TNF-α post-stroke may contribute to the diagnosis and treatment of PSD." (PMID 38377025, 2024). "Additionally, the IL-1β antagonist canakinumab did not reduce recurrent vascular events in patients with stroke in the CANTOS trial." (PMID 36536168, 2024). "VitDlevel showed a positive Pearson correlation with Malat1 (r=0.28, P=0.023) and anegative correlation with IL-1β (r=-0.29, P=0.018) while it could not detect asignificantly negative correlation with stroke severity." (PMID 38974129, 2023). "Regarding TNF-α and IL1-β, there were no level differences related to the stroke time." (PMID 36835156, 2023). "Thus, it is possible that IFNAR1 signaling induces STAT3 activation, leading to the suppression of tPA-enhanced inflammatory molecules, IL-1α, IL-1β and CD86, expression and the promotion of anti-inflammatory molecules, Arg1 and CD206, upregulation in MG in delayed tPA-treated stroke animals." (PMID 37063896, 2023). "Thus, MLC601 and MLC901 reduce infarct size and ischemia-induced neurological deficits, attenuate cerebral ischemia-induced pro-inflammatory cellular infiltration, and attenuate stroke-induced increased expression of pro -inflammatory mediators (IL11, IL1β, IL6 and TNFα) in the brain." (PMID 36975881, 2023).
Stroke (continued). "In addition, butyric acid could inhibit the activation of the microglia and astrocytes in the brains of model mice, thereby inhibiting the generation of pro-inflammatory factors IL-6, IL-1β and TNF-α as well as improving stroke outcomes." (PMID 38201839, 2023). "The panel of biochemical tests should be expanded to include CRP in saliva, and the concentration of IL-1β, OPG, RANKL and MMP-8 in the blood, which would allow for a discussion of the results in saliva in the context of the analyzed role of periodontal disease in the course of stroke." (PMID 35893412, 2022). "Following stroke, the inflamed endothelial cells secrete pro-inflammatory molecules that leak into the brain parenchyma through the damaged BBB and activate the microglia and astrocytes of the neurovascular unit (NVU) which in turn release pro-inflammatory cytokines (TNFa and IL1b)." (PMID 34572411, 2021). "However, clinical data on targeting IL-1β for the purpose of secondary stroke prevention are lacking so far." (PMID 33319833, 2020). "In diabetic patients with lacunar stroke, activation levels of TNFα and IL-1β in the acute phase (24–72 h) and subacute phase (7–10 days) of stroke were lower, compared to non-diabetic patients, which could be associated with their better outcome." (PMID 31701356, 2020). "In order to explore the roles of astrocytes in post-stroke inflammation, the levels of inflammatory factors were detected in primary astrocytes at 0 h, 6 h, 12 h, 24 h, and 48 h after 6-h OGD, including TNF-α, IL-6, IL-10, inducible nitric oxide synthase (iNOS), IL-1β, and CXCL10." (PMID 31426811, 2019). "IL-1β is thought to have a negative effect on stroke recovery." (PMID 30705764, 2019). "Experiments performed by the Lee group showed decreases in the expression of pro‐inflammatory cytokines TNF‐α, IL‐6, IL‐1β, cell adhesion molecules ICAM‐1 and VCAM‐1, and chemokines MCP‐1 and MIP‐1α after intraparenchymal transplantation of fetal‐ and iPSC‐NSCs in a rodent stroke model." (PMID 30747485, 2019). "However, blockade of IL-1β signalling did not alter circulating concentrations of noradrenaline after stroke." (PMID 31700615, 2019). "In addition, the secondary mediators of ischemic cell death and blood-brain barrier disruption, such as IL-6, IL-1β, MMP-3 and iNOS, may constitute useful biomarkers of CKD-induced stroke severity." (PMID 31015533, 2019). "Priming of 3D-MSC spheroids leads to increased levels of MMP-13, particularly after treatment with IL-1β, and so may not have a therapeutic benefit if given in the acute phase after stroke." (PMID 29343288, 2018). "Furthermore, we showed that steppogenin suppressed inducible NF-kB activation and the subsequent induction of proinflammatory mediators, such as NO, PGE2, IL-1β, IL-6, TNF-α, IL-12 and that it blocked the neuronal disorders including Alzheimer’s disease, Parkinson’s disease, and stroke." (PMID 29207498, 2017). "In the same vein, JAK3 inhibition with 10 mg/kg decernotinib did not affect stroke-induced upregulation of Ccl2, Cxcl10, and Cxcl1, chemokines important for immune cell trafficking, nor proinflammatory mediators IL-1β, IL-6, Tnfα, Ptgs2, and Mmp-9 that exacerbate stroke damage." (PMID 28790974, 2017). "Although the direct injection of IL-1β does not result in any overt cell death itself, our findings have important implications for neurological conditions where raised levels of IL-1 have been reported, including stroke and epilepsy." (PMID 27557843, 2016). "With regard to the selected participants for comparing serum IL-1α and IL-1β concentrations, we could not determine whether there was a high proportion of stroke patients with CE, SVD, or any other determined etiology." (PMID 24063019, 2013). "Indeed, TNFα, IL-1α, IL-1β, CCL2, CCL3 and CX3CR1 transcript expression differed in the ischemic cerebral tissue of TREM2-KO mice compared to littermate controls at day 7 after stroke." (PMID 23301011, 2013).
Stroke (continued). "One previous meta-analysis also failed to suggest statistically significant associations of IL-1B-511 and IL-1RN VNTR polymorphisms with stroke risk in the overall population, with ORs and 95%CI of 1.22 (0.85–1.87) for TT vs. CC and 1.22 (0.85–1.75) for RN2/RN2 vs. RN1/RN1." (PMID 23029154, 2012). "Second, doses of anti-IL-1β antibody used in this study may not have been large enough to delay stroke onset." (PMID 23326018, 2012). "There are some reasons that anti-IL-1β antibody did not delay the onset of stroke." (PMID 23326018, 2012). "However, recent studies turned the spotlight on the inflammation, as shown in the CANTOS trial, in which Canakinumab, a human monoclonal antibody targeting IL-1β, reduced the total CV burden expressed as nonfatal myocardial infarction, stroke, or cardiovascular death." (PMID 40428204, 2025). "Interestingly the serum levels of IL-1β and TNF-α exhibited the same pattern as that of MHC II on microglia, and the infiltration of peripheral leukocytes also showed the similar pattern, especially the pattern of lymphocytes that exhibited a close correlation to the stroke outcomes." (PMID 27405096, 2016). "In contrast to IL-1β expression, real-time PCR with the use of caspase-1 specific primers revealed a tendency towards reduced caspase-1 mRNA expression after stroke in MT-II-treated mice when compared to vehicle only treated mice after stroke, however without statistical significance." (PMID 26658636, 2015). "We confirmed that brain IL-6, IL-1β, TNF-α, CCR2, and MCP-1 expression levels were not significantly different between ND/veh and DD/STZ mice prior to stroke (data not shown)." (PMID 35784349, 2022). "In contrast to the brain, stroke markedly increased expression of inflammatory-related factors, including IL-17a, TNFα, and TLR4, in the gut; however, IL-1β and MCP-1 levels were not increased as in the brain." (PMID 34327147, 2021). "On the contrary, for all other cytokines measured (IL-1β, MCP-1, TNF-α, IL-1RA, and IL-6), secretions were reduced only from cocultures with healthy monocytes, and not from stroke-Mo at 24 hours." (PMID 32802081, 2020). "A recent report has issued that CD200R1 is expressed on infiltrating lymphocytes, not on MG, and CD200R1 KO stroke brains showed higher concentrations of TNF‐α and IL‐1β in ischemic brain tissue of KO mice compared with WT controls at day 7 after stroke." (PMID 33067924, 2020). "Whole lung gene expression of IL-1β, TNF-α and MCP-1 was not altered at any of the time-points post stroke, but there was an increase in IL-6 and MIP-2α at the 6 h time-point." (PMID 30842652, 2019). "In subjects with stroke classified as LAAS and metabolic syndrome, PWV was more significantly and positively related to CRP, IL-1β, IL-6, TNF-α, vWF and PAI-1 compared to subjects without metabolic syndrome and the same subtype of stroke." (PMID 24571954, 2014). "Prior to stroke, the basal MCP-1 gene expression in the diabetic peritoneal cells was highly elevated while IL-1β and TNFα were not different between normal and diabetic peritoneal cells (data not shown)." (PMID 24886035, 2014). "In subjects with CEI subtype and metabolic syndrome, PWV was more significantly and positively related to vWF but not with TNF-α, CRP, IL-6, IL-1β and PAI-1 compared to subjects without metabolic syndrome and the same subtype of stroke." (PMID 24571954, 2014). "Histological analysis showed that IL-1β administration slightly increased the incidence of stroke in SHR, even though each lesion was small and did not induce any sighs of stroke onset." (PMID 23326018, 2012). "IL-6 is induced by tumour necrosis factor α and IL-1β, and then leads to the releases of CRP, fibrinogen, and cell adhesion molecules, though the cellular origin of IL-6 after stroke is not clear." (PMID 19901973, 2009).